NFATC4 (nuclear factor of activated T cells 4)
Description:
Ca(2+)-regulated transcription factor that is involved in several processes, including the development and function of the immune, cardiovascular, musculoskeletal, and nervous systems. Involved in T-cell activation, stimulating the transcription of cytokine genes, including that of IL2 and IL4. Along with NFATC3, involved in embryonic heart development. Following JAK/STAT signaling activation and as part of a complex with NFATC3 and STAT3, binds to the alpha-beta E4 promoter region of CRYAB and activates transcription in cardiomyocytes (By similarity). Involved in mitochondrial energy metabolism required for cardiac morphogenesis and function (By similarity). Transactivates many genes involved in the cardiovascular system, including AGTR2, NPPB/BNP (in synergy with GATA4), NPPA/ANP/ANF and MYH7/beta-MHC (By similarity). Involved in the regulation of adult hippocampal neurogenesis. Involved in BDNF-driven pro-survival signaling in hippocampal adult-born neurons. Involved in the formation of long-term spatial memory and long-term potentiation (By similarity). In cochlear nucleus neurons, may play a role in deafferentation-induced apoptosis during the developmental critical period, when auditory neurons depend on afferent input for survival (By similarity). Binds to and activates the BACE1/Beta-secretase 1 promoter, hence may regulate the proteolytic processing of the amyloid precursor protein (APP). Plays a role in adipocyte differentiation. May be involved in myoblast differentiation into myotubes. Binds the consensus DNA sequence 5'-GGAAAAT-3' (Probable). In the presence of CREBBP, activates TNF transcription. Binds to PPARG gene promoter and regulates its activity. Binds to PPARG and REG3G gene promoters (By similarity).
Synonyms: NF-ATc4; NF-AT3; NFAT3
Tractability: PROTAC: UniProt records ubiquitination sites on it; ubiquitination databases record sites on it.
Gene: Protein-coding gene on chromosome 14 (24,365,673 to 24,379,604, forward strand). Ensembl gene ENSG00000100968.
Subcellular location: Cytoplasm; Nucleus
Subcellular location (Human Protein Atlas): Cytosol; Nuclear speckles
Gene Ontology:
Molecular function: DNA-binding transcription repressor activity, RNA polymerase II-specific; protein binding; sequence-specific double-stranded DNA binding; DNA-binding transcription factor activity, RNA polymerase II-specific; RNA polymerase II cis-regulatory region sequence-specific DNA binding; transcription cis-regulatory region binding; DNA binding; DNA-binding transcription factor activity
Biological process: negative regulation of miRNA transcription; brain-derived neurotrophic factor receptor signaling pathway; calcineurin-NFAT signaling cascade; inflammatory response; long-term memory; long-term synaptic potentiation; negative regulation of neuron apoptotic process; positive regulation of transcription by RNA polymerase II; negative regulation of transcription by RNA polymerase II; negative regulation of Wnt signaling pathway; regulation of DNA-templated transcription
Cellular component: cytoplasm; cytosol; nuclear speck; nucleus; chromatin; transcription regulator complex
Genetic constraint (gnomAD): Loss-of-function variants: 25 observed, 69.88 expected, observed/expected ratio (o/e) 0.36, 90% interval 0.26 to 0.5. The upper end of that interval is the gene's LOEUF score, 0.5, which puts it in group 2 of 6, group 1 being the genes least tolerant of losing a copy. Missense variants: 1,130 observed, 1,212.9 expected, observed/expected ratio (o/e) 0.93, 90% interval 0.89 to 0.98. Synonymous variants: 523 observed, 514.49 expected, observed/expected ratio (o/e) 1.02, 90% interval 0.94 to 1.09.
Homologues: Orthologues: chimpanzee NFATC4 (99% identical), macaque NFATC4 (97% identical), rabbit NFATC4 (95% identical), dog NFATC4 (95% identical), guinea pig NFATC4 (95% identical), pig NFATC4 (95% identical), mouse Nfatc4 (93% identical), rat Nfatc4 (91% identical), tropical clawed frog nfatc4 (58% identical), zebrafish nfatc4 (44% identical). Paralogues in human: NFATC3 (44% identical), NFATC1 (34% identical), NFATC2 (33% identical), NFAT5 (21% identical).
Diseases named in the same sentence as NFATC4 in open-access papers:
NFATC4 is named in the same sentence as 82 diseases in open-access papers, as found by Europe PMC text mining. Sharing a sentence is not in itself a finding about the gene and the disease. The quoted sentences say what the papers report.
cardiac hypertrophy (44 papers, 2011 to 2025). "miR-133 can regulate cardiac hypertrophy, both in vivo and in vitro, targeting different genes such as, for example, the β-adrenergic receptor, or the hypertrophy-associated mediator NFATc4." (PMID 34574061, 2021). "Since the dysregulation of NFATC4 has been linked to disorders such as breast and ovarian cancer as well as cardiac hypertrophy, the development of blockers specifically targeting the Cn/NFATC4 interaction could be used as a therapeutic strategy for multiple diseases." (PMID 37310791, 2023). "NFATc4, a regulator of cardiac hypertrophy, remains highly phosphorylated and inactive under baseline conditions, but its dephosphorylation activates itself and contributes to cardiac hypertrophy." (PMID 39334239, 2024). "Mechanically, Mettl1 increases SRSF9 expression by inducing m7G modification of SRSF9 mRNA, facilitating alternative splicing and stabilization of NFATc4, thereby promoting cardiac hypertrophy." (PMID 38810124, 2024). "In the pathway for the role of NFAT in cardiac hypertrophy, histone deacetylase 7 and NFATc4 were both hypermethylated." (PMID 35336913, 2022). "A cell model of cardiac hypertrophy and heart failure showed that miR-29 over-expression inhibits cardiomyocyte hypertrophy via inhibiting NFATc4 expression." (PMID 34574061, 2021). "The development of cardiac hypertrophy was confirmed by the increased activity of NFATc4, a marker for cardiac hypertrophy signaling." (PMID 33644136, 2021). "A number of transcription factors (e.g., nuclear factor of activated T cells 4 [NFATc4], nuclear factor kappa B [NF-κB], and mitogen-activated protein kinases [MAPKs, e.g., Akt and Erk1/2]) are involved in cardiac hypertrophy signaling." (PMID 29670896, 2018). "NFATc4, a member from the Nuclear Factor of Activated T cells (NFATs) transcription factor family, plays a pivotal role in the development of cardiac hypertrophy." (PMID 30670969, 2018). "Calcineurin activation leads to the dephosphorylation of NFATc4, allowing its nuclear localization where it cooperates with other transcription factors to participate in the cardiac hypertrophy." (PMID 27907007, 2016). "Phosphorylated NFATc4 (Nuclear Factor of Activated T cells, cytoplasmic, calcineurin-dependent 4) was used to assess activation and onset of cardiac hypertrophy." (PMID 25337914, 2014). "One of the major mechanisms of cardiac compensation is hypertrophy of the heart and the transcription factor, NFATc4, is one of the well-studied regulators of cardiac hypertrophy." (PMID 25337914, 2014). "Decreased phosphorylation of NFATc4 indicates increased activity, suggesting activation of cardiac hypertrophy signaling in both proton and 56Fe ion-irradiated hearts over 10 months." (PMID 25337914, 2014). "The calcineurin-dependent NFAT isoform c4 (NFATc4) has previously been found to be sufficient for cardiac hypertrophy and to be activated in the hypertrophic human myocardium, and thus activation of this isoform was investigated in our study." (PMID 22164265, 2011). "However, when GSK3β’s kinase activity is inhibited it cannot phosphorylate NFATC4, which remains in the nucleus—promoting cardiac hypertrophy." (PMID 33673453, 2021). "Fenofibrate attenuates pressure overload-induced cardiac hypertrophy partly by inhibiting the binding of p65-NFκB to NFATc4, the c-Jun NH2-terminal kinase pathway, ERK activation, and MMP2 activity, as well as increasing high mobility group box 1 (HMGB1) levels in nuclei." (PMID 30105051, 2018). "A recent study demonstrated that NFATc4 and NF-κB could interact and assemble a transcriptional complex that effectively coordinates cardiac hypertrophy and pathological remodeling." (PMID 29670896, 2018). "Moreover, transgenic mice that overexpress active calcineurin or NFATc4 in the heart develop massive cardiac hypertrophy." (PMID 27746739, 2016). "A potential role in cardiac hypertrophy has been shown for NFATc2, NFATc3, and NFATc4." (PMID 26617522, 2015).
cardiac hypertrophy (continued). "In terms of molecular signaling there was an activation of NFATc4 in proton-irradiated hearts that may indicate activation of cardiac hypertrophy signaling." (PMID 25337914, 2014). "There was activation of NFATc4 in 56Fe ion-irradiated hearts that may indicate activation of cardiac hypertrophy signaling." (PMID 25337914, 2014). "However, it is possible that cardiac piRNA expression has downstream effects on cellular signaling pathways that involve GSK3β, which is a known repressor of cardiac hypertrophy by phosphorylating proteins involved in cell proliferation such as β-catenin and NFATC4." (PMID 33673453, 2021). "The intersection of these databases yielded genes known to be involved in cardiac hypertrophy, including EZH2, NFATc4, GATA4, and JARID2." (PMID 38810124, 2024). "Cardiac hypertrophy and diastolic dysfunction (after 1 month) and increased cardiac fibrosis (after 3 months), as indicated by increased LVEDP and NFATc4 activity." (PMID 33644136, 2021). "Our study suggests that dronedarone produces inhibition of the NFATc4/ERK/AKT pathway and improvement of thiol-specific oxidative stress possibly secondary to the reduction of blood pressure in an animal model of ventricular hypertrophy." (PMID 32982770, 2020). "In conclusion, our study suggests that dronedarone produces inhibition of the NFATc4/ERK/AKT pathway and improvement of thiol-specific oxidative stress possibly secondary to the reduction of blood pressure in an animal model of ventricular hypertrophy." (PMID 32982770, 2020). "NFATc4, one of five NFAT family members, was shown to be capable of promoting cardiac hypertrophy in vivo." (PMID 29670896, 2018). "NFATc4 has been described as a new mechanism that contributes to the induction of pathological cardiac hypertrophy Interestingly, short-term treatment of SHR with esmolol significantly reduced p-NFATc4 levels." (PMID 29670896, 2018). "The signaling cascades of the mitogen activated protein kinase (MAPK) family, calcineurin/NFATc4, and PI3K/Akt/GSK3, are believed to participate in endothelin-1 (ET-1)-induced cardiac hypertrophy." (PMID 26056815, 2015). "This study reveals that METTL1 plays an important role in driving cardiac hypertrophy by regulating the SRSF9/NFATc4 axis, suggesting that targeting METTL1 could be an efficient way to treat cardiac hypertrophy and HF." (PMID 39979979, 2025). "Similarly, SIRT6 downregulated the expression of NFATc4 and deacetylated NFATc4 to promote its nuclear export, thereby reducing BNP expression and protecting against cardiac hypertrophy." (PMID 36465178, 2022). "Early systolic and diastolic decompensation (after 1 month) and cardiac hypertrophy (after 3 months), as indicated by an increase in LV posterior wall thickness (PWth), LV end-diastolic pressure (LVEDP), dP/dtmin, ejection fraction % (EF%) and NFATc4 activity." (PMID 33644136, 2021). "Cardiac hypertrophy (after 3 months) as indicated by an increase in LV posterior wall thickness (PWth), LV end-diastolic pressure (LVEDP), dP/dtmin, ejection fraction % (EF%) and NFATc4 activity." (PMID 33644136, 2021). "Our results demonstrated that FKBP12.6 protects heart from AngII‐induced cardiac hypertrophy through preventing the activations of the Ca2+/calmodulin‐dependent signalling pathways such as calcineurin/NFATc4, CaMKII/MEF‐2, AKT/GSK3β/NFATc4 and AKT/mTOR pathways." (PMID 29682889, 2018). "NFATc4, a member of nuclear factor of activated T cells (NFAT) transcription factor family, has been well-documented for its involvement in several diseases including cardiac hypertrophy, by regulating various target genes." (PMID 30670969, 2018). "NFATc4 knock-out mice do not show compromised hypertrophic growth, although c4 overexpression results in massive cardiac hypertrophy." (PMID 39086965, 2022). "Thus, canstatin might inhibit cardiac hypertrophy in the non-infarcted area perhaps in part through the suppression of Ca2+/calcineurin/NFATc4 pathway after MI." (PMID 32732948, 2020).
breast carcinoma (8 papers, 2009 to 2022). "NFATc4/ERα and NFATc4/ERβ inhibited the transcriptional activity of IL-2 in breast cancer cells, especially ERα." (PMID 35698138, 2022). "NFATc4 is overexpressed in breast cancer with 65% positive in cancerous tissue and 15% positive in noncancerous tissue." (PMID 35698138, 2022). "It has been shown that the expression of NFATc4 can be detected in breast cancer cells and a subset of breast cancer patients." (PMID 35698138, 2022). "Accumulated evidences have indicated that NFATc4 plays essential roles in regulating the proliferation, invasion and migration of breast cancer cells." (PMID 35698138, 2022). "EVs produced by breast cancer cells expressing NFATc4 inhibited cell invasion effectively among different types of cancer cell lines (triple negative breast cancer, invasive melanoma, glioblastoma, and pancreatic cancer)." (PMID 35698138, 2022). "We demonstrated that the transcription factor NFAT1 (NFATc2) exerts a pro-invasive function, whereas NFAT3 (NFATc4) has anti-invasive properties limiting the aggressiveness of primary NFAT3-expressing luminal breast cancer cells." (PMID 32488182, 2020). "On the other hand, little is known about the specific roles of NFATc3, NFATc4, and NFAT5 in tumorigenesis and tumor progression, although inhibition of breast cancer cell motility by NFATc4 has been reported." (PMID 25638160, 2015). "Based on survival analysis, NFATc4 is an unfavorable prognostic factor in breast cancer." (PMID 35698138, 2022). "NFATc4 also shows potential regulation of these aspects in breast cancer cells." (PMID 35698138, 2022). "In addition, NFATc4 down-regulated during (E)-4-chloro-2-((3-ethoxy-2-hydroxybenzylidene) amino) phenol (ACES) induced apoptosis through p38-β/SAPK in MCF-7 breast cancer cells, indicating that NFATc4 could be a latent cancer therapeutic target." (PMID 35698138, 2022). "Indeed, NFAT1 (NFATc2) exerts a pro-invasive function and is mainly expressed in the triple-negative subtype, whereas NFAT3 (NFATc4) has anti-invasive properties, limiting the aggressiveness of primary NFAT3-expressing luminal breast cancer cells." (PMID 35847954, 2022). "On the another hand, NFATc4 presenting high expression at mRNA and protein levels in ERα-positive cells repressed LCN2 and led to inhibition of invasion and migration capacities of breast cancer cells." (PMID 35698138, 2022).
glioma (8 papers, 2017 to 2024). A benign or malignant brain and spinal cord tumor that arises from glial cells (astrocytes, oligodendrocytes, ependymal cells). "miR-133b and miR-532-3p play important regulatory roles in suppressing glioma and colorectal cancer through the Wnt/β-catenin signaling pathway, respectively, and NFATC4 resists C. perfringens type C infection in piglets through the Wnt signaling pathway." (PMID 37185732, 2023). "It was previously reported that Nfatc4 works upstream of Tnf-induced apoptosis of glioma cells, and the recruitment of Nfatc4 to the Tnf promoter has been shown to be required in ultraviolet radiation-induced cell death in mouse embryonic fibroblasts." (PMID 31379853, 2019). "In glioma cells, Nfatc4 activation is a prerequisite for the induction of DOX-mediated apoptosis." (PMID 31379853, 2019). "However, in other tissues, such as glioma cells and renal tubular cells, Nfatc4 mediates cell apoptosis." (PMID 31379853, 2019). "Moreover, we identify GRNs (for example, GLI2 and NFATC4) that have not yet been implicated in normal development and may hence present glioma-specific regulatory aberrations." (PMID 36471067, 2022). "Six of those genes were found in three of the six most enriched ‘glioma TADs’: 2160 (CDK4, TSFM, TSPAN31, B4GALNT1), 2337 (NFATC4) and 2688 (CACNA1G)." (PMID 34341417, 2021).
ovarian carcinoma (8 papers, 2020 to 2024). A malignant neoplasm originating from the surface ovarian epithelium. "Recently, the transcription factor NFATC4 (nuclear factor of activated T cells cytoplasmic 4) was identified as a regulator of quiescence in ovarian cancer, enriched in ovarian CSCs and associated with chemotherapy resistance and poor prognosis." (PMID 35582310, 2021). "Besides, NFATc4 acted as a risk factor in the survival of ovarian cancer analyzed from the GSE26193 dataset." (PMID 35698138, 2022). "Another transcriptional factor, such as NFATC4, has been recognized as a potential marker of dormant tumor cells in ovarian cancer." (PMID 38418814, 2024). "NFATC4 was shown to be enriched in a population of slowly dividing cancer stem cells of ovarian cancer." (PMID 38418814, 2024). "Nuclear factor of activated T cells cytoplasmic 4 (NFATC4) drives a quiescent phenotype in ovarian cancer and promotes chemotherapy resistance in vitro and in vivo." (PMID 36890838, 2023). "Their study revealed that the transcription regulator nuclear factor of activated T cells 4 (NFATC4) induces a quiescent state in ovarian cancer and translocates to the nucleus in response to chemotherapy." (PMID 36501221, 2022). "As a transcriptional factor, activated NFATc4 took part in ovarian cancer progression in various regulatory ways." (PMID 35698138, 2022). "Our study discovered that high expression of NFATC4 was associated with poor prognosis of AML, which was consistent with reports in pancreatic cancer and ovarian cancer." (PMID 33329712, 2020). "Accumulating studies identified that NFATc4 is involved in the ovarian cancer, too." (PMID 35698138, 2022).
pancreatic cancer (8 papers, 2016 to 2024). "Whilst the alternate donor site (AD) event in NFATC4 has been identified as a poor prognostic indicator for overall survival in gastric cancer, its association with overall survival appears to be the opposite in pancreatic cancer." (PMID 37924098, 2023). "In acinar cell plasticity and pancreatic cancer initiation, NFATc4 was found to be overexpressed and localized in the nucleus, thus activating the inflammation-induced epidermal growth factor receptor signaling pathway and upregulating the expression of Sox9." (PMID 33511023, 2021). "NFATc4 could play a pivotal role in caerulein-induced pancreatic cancer initiation through NFATc4 transcriptional overexpression of SOX9." (PMID 35698138, 2022).
colon cancer (7 papers, 2011 to 2023). "For example, NFATc1 promotes proliferation of hepatocellular carcinoma cells, NFATc2 increases the invasiveness of breast cancer cells, and NFATc3 and NFATc4 promote the progression of colon cancer." (PMID 28881766, 2017). "Conversely, hypomethylation and upregulated oncogene functions of HIST1H3I (Histone linker 1 with Histone H3.1), HIST1H3D (Histone linker 1 with Histone H3.D), NFATC4 (Nuclear factor of activated T-cells cytoplasmic 4) and HOXB8 (Homeobox B8) were associated with adiposity and colon cancer." (PMID 35629083, 2022). "NFATc4 is also involved in colon cancer, another digestive system neoplasm." (PMID 35698138, 2022). "NFATc2 likely opposes the action of NFATc1, NFATc3, and NFATc4 in colon cancer cells as those tumors lacking NFATc2 expression most likely had a more aggressive clinical course driven in part by the unopposed actions of NFATc1, NFATc3, and NFATc4." (PMID 26795951, 2016).